LRP3 (LDL receptor related protein 3)
Description:
Probable receptor, which may be involved in the internalization of lipophilic molecules and/or signal transduction. Its precise role is however unclear, since it does not bind to very low density lipoprotein (VLDL) or to LRPAP1 in vitro.
Synonyms: LRP-3; hLRp105
Tractability: Antibody: UniProt predicts a signal peptide or a membrane-spanning region; its Gene Ontology location is reachable by antibodies, with medium confidence. PROTAC: its protein half-life has been measured.
Gene: Protein-coding gene on chromosome 19 (33,177,603 to 33,208,864, forward strand). Ensembl gene ENSG00000130881.
Subcellular location: Membrane; Membrane, coated pit
Subcellular location (Human Protein Atlas): Lipid droplets
Gene Ontology:
Biological process: negative regulation of fat cell differentiation; negative regulation of gene expression; positive regulation of gene expression; positive regulation of osteoblast differentiation; receptor-mediated endocytosis; transport across blood-brain barrier; vesicle-mediated transport
Cellular component: membrane; plasma membrane
Genetic constraint (gnomAD): Loss-of-function variants: 48 observed, 48.77 expected, observed/expected ratio (o/e) 0.98, 90% interval 0.78 to 1.25. The upper end of that interval is the gene's LOEUF score, 1.25, which puts it in group 5 of 6, group 1 being the genes least tolerant of losing a copy. Missense variants: 995 observed, 949.7 expected, observed/expected ratio (o/e) 1.05, 90% interval 0.99 to 1.1. Synonymous variants: 467 observed, 403.73 expected, observed/expected ratio (o/e) 1.16, 90% interval 1.07 to 1.25.
Homologues: Orthologues: chimpanzee LRP3 (99% identical), macaque LRP3 (98% identical), pig LRP3 (95% identical), dog LRP3 (94% identical), mouse Lrp3 (93% identical), rat Lrp3 (93% identical), guinea pig LRP3 (92% identical), rabbit LRP3 (91% identical), tropical clawed frog lrp3 (60% identical), zebrafish lrp3 (56% identical), Drosophila melanogaster arr (7% identical). Paralogues in human: LRP12 (43% identical), LRP10 (34% identical), LRP1 (25% identical), LRP1B (25% identical), LRP2 (22% identical), VLDLR (18% identical), LRP8 (17% identical), NID2 (15% identical), NID1 (14% identical), LRP4 (14% identical), EGF (12% identical), and 2 more.
Diseases named in the same sentence as LRP3 in open-access papers:
LRP3 is named in the same sentence as 12 diseases in open-access papers, as found by Europe PMC text mining. Sharing a sentence is not in itself a finding about the gene and the disease. The quoted sentences say what the papers report.
Alzheimer disease (2 papers, 2021). A progressive, neurodegenerative disease characterized by loss of function and death of nerve cells in several areas of the brain leading to loss of cognitive function such as memory and language. "We have estimated LRP3 expression in the frontal cortex of middle-aged (MA) individuals and in cases with Alzheimer’s disease (AD)-related pathology, and after overexpression in CHO cells." (PMID 34727970, 2021). "We analyzed LRP3 expression in middle-aged individuals (MA) and in cases with Alzheimer’s disease (AD)-related pathology, and the relation of LRP3 with APP." (PMID 34727970, 2021).
autoimmune disease (1 paper, 2018). A disorder resulting from loss of function or tissue destruction of an organ or multiple organs, arising from humoral or cellular immune responses of the individual to their own tissue constituents. "A recent study has demonstrated that the LRP3 inflammasome plays a critical role in the pathogenesis of many autoimmune diseases." (PMID 30140708, 2018).
candidiasis (1 paper, 2022). Infection with the organism Candida. "The association of LRP3 expression with candida infection in esophageal mucosa was interesting because the esophagus is a well-described site of candida infection." (PMID 36167494, 2022). "The replication of this LRP3/candidiasis and WDR88/candidiasis association in various tissues suggests that there may be mechanisms common across tissues." (PMID 36167494, 2022). "An additional new observation was an association between the WDR88/LRP3 region and the risk of candidiasis; further, TWAS also showed that the genetically determined expression of WDR88 and LRP3 in a variety of tissues associated with altered risk of candidiasis." (PMID 36167494, 2022). "In TWAS, four gene-disease associations were significant: SLC30A9 for otitis media (p = 8.06 × 10–7); LRP3 and WDR88 for candidiasis (p = 3.91 × 10–7 and p = 1.95 × 10–6); and AAMDC for hepatitis B (p = 1.51 × 10–6)." (PMID 36167494, 2022). "LRP3 encodes LDL receptor related protein 3, which is involved in the internalization of lipophilic molecules, but whether LRP3 could affect the risk of candida infection through this mechanism is not known." (PMID 36167494, 2022).
osteoarthritis (1 paper, 2022). A noninflammatory degenerative joint disease occurring chiefly in older persons, characterized by degeneration of the articular cartilage, hypertrophy of bone at the margins and changes in the synovial membrane. "Regardless of diet, LRP3 overexpression in cartilage attenuate anterior cruciate ligament transection induced osteoarthritis progression in rats and Lrp3 knockout-induced osteoarthritis progression in mice." (PMID 36414669, 2022). "This study demonstrates a role of cholesterol metabolism-related gene, Lrp3, in cartilage degeneration and osteoarthritis pathogenesis." (PMID 36414669, 2022). "We identify syndecan-4 as a downstream molecular target of LRP3 in osteoarthritis pathogenesis." (PMID 36414669, 2022).
trauma (1 paper, 2022). "In order to further clarify the relationship between the expression of LRP3 and OA, we first collected cartilage tissues from five trauma patients (as control) and five OA patients." (PMID 36414669, 2022).
cancer (1 paper, 2021). A tumor composed of atypical neoplastic, often pleomorphic cells that invade other tissues. "And based on qRT-PCR results, after overexpressing miR-744-5p, the expression level of UBE2L3 was inhibited in cancer cells but no significant changes were presented in LRP3 and NFIX expression." (PMID 33726770, 2021).
LRP3 also shares sentences with these, for which no sentence is quoted: fibrosarcoma (1 paper); hepatitis B (1); melanoma (1); Neurofibrillary tangles (1); otitis media (1); sarcoma (1).